MGMT (O-6-methylguanine-DNA methyltransferase)
Diseases named in the same sentence as MGMT in open-access papers (continued):
Sharing a sentence is not in itself a finding about the gene and the disease.
tumor (continued). "The checkpoint molecule B7-H3 (CD276) is statistically increased in MGMT methylated tumour cores compared with unmethylated tumour cores of GBMs (p = 0.023); MGMT methylated tumour core counts: 14.07 [1.02] compared to MGMT unmethylated GBM (tumour core: 12.35 [0.87])." (PMID 33995529, 2021). "PCI-24781 significantly inhibited tumor growth and downregulated DNA repair machinery (BRCA1, CHK1, RAD51, and O6-methylguanine-DNA- methyltransferase (MGMT)), increasing DNA double-strand breaks and causing apoptosis in the GBM cell lines, including an MGMT expressing cell line in vitro." (PMID 34696786, 2021). "MGMT methylation, in particular, is a prognostic marker of response to TMZ—at recurrence, evolutionary pressures from treatment and further tumor mutations may cause significant changes in the disease biology separate from its initial genotypic profile." (PMID 34042101, 2021). "Baseline dexamethasone use as well as lack of tumor MGMT methylation and IDH1 mutation correlated with poorer OS." (PMID 33810532, 2021). "However, the limited MGMT protection threshold can be overwhelmed within the tumor with targeted BSH delivery." (PMID 33419160, 2021). "It has been speculated that endothelial permeability in MGMT-methylated GBM could be related to a better temozolomide penetration in the tumor." (PMID 33498680, 2021). "Next, we generated a multivariate Cox proportional hazards (CPH) model that included the expression levels of POLD1 and RAD51 and other common clinical prognostic factors (patient age, KPS group, tumor size, extent of resection, IDH mutational status, and MGMT promotor methylation status)." (PMID 34771522, 2021). "Patients with MGMT promoter-methylated tumours survived longer." (PMID 32748120, 2021). "Interestingly, our control group demonstrated significant tumor size difference depending on MGMT methylation, with MGMT methylated tumors demonstrating smaller size." (PMID 34199376, 2021). "Among examples of the influence of DNA methylation on tumor sensitivity to treatment, MGMT promoter methylation downregulates MGMT expression, disrupting MGMT role in DNA repair, which is linked to resistance to nitrosourea-based antitumor agents, temozolomide, and radiation." (PMID 33676569, 2021). "Decreased MGMT protein expression levels in malignant thyroid lesions may result in tumor progression and/or progression of thyroid neoplasia, in line with evidence from other types of cancer." (PMID 33976347, 2021). "Therefore, the capability of MGMT hypermethylation to serve as a biomarker for neoplasms or as indicator of malignant transformation of precancerous lesions is highly reduced by our results." (PMID 33917711, 2021). "The expression of MGMT seems to correlate with response of a tumor to the TMZ therapy." (PMID 33841328, 2021). "Consequently, MGMT has emerged as a central determinant of tumor resistance to clinically used alkylating agents." (PMID 33801310, 2021). "Interestingly, this finding was only significant in GBMs with a methylated MGMT promoter which suggests an important anti-inflammatory role of miRNA93 expression as a tumor suppressor in GBM patients with hypermethylated MGMT promoters." (PMID 33747971, 2021). "The reason for this difference is uncertain, although MGMT unmethylated tumors may have aggressive features that lead to larger tumor size." (PMID 34199376, 2021). "However, systemic administration leads to MGMT inactivation not only in the tumor, but also in the healthy tissue throughout the body." (PMID 34639014, 2021). "Previous studies on MGMT status and tumor location are conflicting." (PMID 33742279, 2021). "We hypothesized that the shorter survival of patients with MGMT-unmethylated GBM is partly due to the pro-tumor immune response." (PMID 33614641, 2021).
tumor (continued). "According to their study, circ-Foxo3 expression was not only significantly associated with tumor size and histologic grade but was also related to wild-type isocitrate dehydrogenase (IDH) expression and O6-methylguanine DNA methyltransferase (MGMT) methylation status." (PMID 33833780, 2021). "Prognostic factors for adult diffuse gliomas include age, gender, performance status, the extent of tumor resection, and intrinsic factors of the tumor including grade, isocitrate dehydrogenase (IDH) mutation, chromosome 1p/19q status, and MGMT promoter methylation." (PMID 34413349, 2021). "The intracranial GBM mouse model also demonstrated that the synergy between PP and TMZ could be achieved through down-regulating β-catenin and MGMT, which prolonged the survival time of tumor-bearing mice." (PMID 34642308, 2021). "MGMT is silenced during the oncogenesis of several human cancer types, leading to inefficient repair of DNA alkylation, and resulting in increased sensitivity to alkylating agents and decreased tumor survival." (PMID 34944843, 2021). "However, tumor O6-methyl-guanine-DNA-methyltransferase (MGMT) promoter methylation status is considered a prognostic factor, and an obstacle that cannot be overcome by the initial induction therapy and 6 subsequent cycles (C) of maintenance treatment with TMZ." (PMID 34320929, 2021). "However, the correlations were not significant between EVA1C expression and age, gender, history of radiotherapy or chemotherapy, MGMT promoter methylation, as well as tumor recurrence." (PMID 34267752, 2021). "In the multivariate Cox analysis, MGMT promoter methylation status [unmethylated vs. methylated, P = 0.002, HR = 3.560 (1.600–7.920)] and tumor type [primary vs. recurrent/secondary, P = 0.010, HR = 0.384 (0.186–0.794)] remained significantly correlated with OS." (PMID 33628600, 2021). "If the tumor is too large for surgery or the tumor volume is felt to be too large for save radiation in someone with poor clinical status and they are known to have a MGMT promoter methylated tumor, they may be offered TMZ alone." (PMID 34206775, 2021). "As tumor cells within the ventricle system seeded during surgery are less likely to be colonized, a relatively small dose may have been successful in eradicating the tumor cells, even in patients with MGMT-unmethylated GBMs." (PMID 34621677, 2021). "This implies that MGMT methylation assessment may provide incomplete information regarding prognosis, and that adding the characterization of tumor vascularization may improve estimation of responsiveness to TMZ." (PMID 33001310, 2021). "TMZ triggers cytotoxicity increase and cell apoptosis of GBM tumor cells by alkylating the O6-position of guanine, while MGMT is the protein that allows DNA repair by removing the alkyl group from the O6-position of guanine and eventually results in tumor resistance to alkylating agents." (PMID 34970146, 2021). "Importantly, this method allowed for successful validation of the MGMT status model, improving comparability between cohorts, while preserving information about tumor biology." (PMID 33937035, 2021). "Tumor tissue samples were available from 83% of the patients for MGMT testing." (PMID 34692470, 2021). "Taken together, we provide further evidence for sex-bound disparities in the epigenetic regulation of IDHwt GBM, exemplified by the MGMT status of the tumor, which could contribute to a survival advantage for female patients." (PMID 33546098, 2021).
tumor (continued). "In case of recurrent tumor surgery, MGMT methylation status could be verified in all patients and was identical in 100% to the MGMT status of the tissue resected in the primary surgery." (PMID 34185258, 2021). "In these tumours, the MGMT promoter is usually unmethylated." (PMID 33293629, 2021). "First, imipramine may inhibit ERK/NF‐κB signalling transduction and thus reduced tumour progression‐related proteins expression, including MGMT, MMP‐2, MMP‐9, uPA, VEGF, Cyclin D1 and XIAP." (PMID 32149465, 2020). "Therefore, information on the extent of tumor resection (n = 1), MGMT promoter methylation (n = 14), and Ki67 staining (n = 3) is missing for some patients." (PMID 32635204, 2020). "The algorithm relied on the clinical variables that showed a significant impact as independent predictor factors in multivariate analysis (age, EOR, MGMT methylation status, preoperative ΔT1/T2 MRI Index, preoperative volumetric tumor volume on T2- weighted images." (PMID 32046132, 2020). "There were only three patients in group 1 who had a tumor with MGMT promotor methylation status." (PMID 33374196, 2020). "Measurement of MGMT expression might help assess the tumor sensitivity to TMZ but this still needs to be systematically investigated." (PMID 32132978, 2020). "Well-known biomarkers in neuro-oncology include demographic features (such as age) and tumour features (such as grade and O6-methylguanine-DNA methyltransferase [MGMT] promoter methylation status), while imaging biomarkers are used for diagnosis, prognosis, and treatment response monitoring." (PMID 31371027, 2020). "In the univariate analysis for LGG, we used MAGEH1 expression, MAGED1 expression, age, gender, tumor histology, WHO grade, IDH mutation status, 1p/19q codeletion status, and MGMT promoter methylation status to analyze the association of these variables to patient outcome." (PMID 33425727, 2020). "GI-NETs are generally characterized as neoplasms with relatively abundant MGMT." (PMID 33287738, 2020). "MGMT can inhibit the killing effect of alkylating agents on tumor cells by chromosome protection." (PMID 32141507, 2020). "MGMT promoter hypermethylation was detected by MS‐qPCR in 19 of 43 (44.2%) tumours." (PMID 31111685, 2020). "Interestingly, they reached significant results for correlations of MGMT promoter methylation with clinicopathological markers such as tumor staging and grading and estrogen and progesterone receptor expression." (PMID 32841306, 2020). "Results from this experiment indicate that the four primary GBM tumors demonstrate significant differences in both the levels and localization of MGMT, reflective of a highly irregular tumor microenvironment and local oxidative stresses experienced by the tumors." (PMID 32075134, 2020). "Hence, it is possible that proportion of MGMT methylation itself differs between tumor grade in different race." (PMID 33247700, 2020). "Most of these studies defined MGMT promoter methylation using data from the primary tumor." (PMID 33375286, 2020). "Although not evidence-based, this strategy has been common practice in our region for elderly and frail patients with unknown MGMT methylation status and extensive tumor spread." (PMID 32053655, 2020). "In a study, MGMT methylation was mainly observed in tumors with a higher percentage of contrast-enhancing tumor volume to complete tumor volume, higher Gaussian-normalized relative cerebral blood volume (nrCBV) and nrCBV in the contrast-enhanced and total tumor volumes." (PMID 33575207, 2020). "Thus, patients with MGMT methylation are prone to tumors and tumor invasion, but the treatment effect is good." (PMID 32141507, 2020). "MGMT, therefore, protects not only normal cells from apoptosis but also tumor cells." (PMID 32354046, 2020).
tumor (continued). "Many prior studies have demonstrated that certain quantitative image features (e.g. tumor subcompartment ratios, diffusivity values, and image texture features) can be used to predict both IDH mutations and MGMT hypermethylation on preoperative imaging of gliomas." (PMID 32678261, 2020). "However, MGMT methylation status identification methods, where the tumor tissue is often undersampled, are time consuming and expensive." (PMID 32942564, 2020). "Age at diagnosis, sex, KPS, IDH mutation status, MGMT methylation status, pre-operative CE tumor volume, pre-operative NCE tumor volume, EOR-CE and EOR-NCE were possible prognostic risk factors for univariate analysis for the derivation cohort of patients with nGBM." (PMID 33344248, 2020). "The multivariate analysis showed age (hazard ratio [HR], 1.02; P < 0.001), postoperative KPS score (HR 0.99; P = 0.002), complete tumour resection (HR 0.52; P < 0.001), MGMT promoter methylation (HR 0.75; P < 0.001), and LEV use (HR 0.72; P = 0.011) were significantly associated with OS." (PMID 32612203, 2020). "TERT promoter mutation C250T and MGMT promoter methylation was significantly associated with tumor growth in univariable analysis but not in multivariable analysis." (PMID 32388499, 2020). "Fourth, in addition to MGMT status, the treatment effect may also be affected by the location of the primary tumor, the extent of metastasis, and the response to surgery." (PMID 32141507, 2020). "The algorithm relied on six clinical variables that shows the interaction between the significant variables at multivariate analysis (age, EOR, MGMT methylation status, preoperative ΔT1/T2 MRI index, pre-operative volumetric tumor volume on T2-weighted images and intraoperative protocol)." (PMID 32046132, 2020). "Patients without MGMT methylation had a low risk of carcinogenesis because of high MGMT expression and an advanced DNA repair effect; however, when a tumor is established, the effect of chemotherapy and life expectancy are poor." (PMID 32141507, 2020). "Finally, a combinational analysis was performed to estimate the importance of tumoral and exosomal miR-181 levels, IDH1 and MGMT status, tumor related symptoms, quality of life index, and functional patients’ status for the survival outcome prediction." (PMID 33050332, 2020). "The finding of a very high fraction of MGMT-methylated tumours having simultaneous high EGR1 expression raises the question whether EGR1 is involved in methylation of the MGMT promoter." (PMID 32518380, 2020). "Tumor sections treated with O6PGG/azido-PEG-FITC/click show active MGMT levels." (PMID 32075134, 2020). "Similarly, when PFS was considered, univariate Cox regression analyses confirmed age (p = 0.000), EOR (p = 0.000), methylation status of MGMT promoter (p = 0.000) and preoperative ΔT1/T2 MRI Index (p = 0.000) as factors influencing the tumor progression." (PMID 32046132, 2020). "It found 4 of 5 MGMT-deficient patients get tumor response after treatment, and none of 16 MGMT-proficient patients get tumor response." (PMID 32141507, 2020). "Additionally, GBM patients that survived longer than an expected 12-month period and had an unmethylated O-6-methylguanine methyltransferase (MGMT) promoter also had a significantly higher miR-181d expression in their tumor tissue (p < 0.05)." (PMID 33050332, 2020). "However, it is important to highlight the need of further studies and clinical trials to define, for each subtype of HNSCC tumor, the actual diagnostic and predictive value of DAPK and MGMT as well as its viability and efficacy in clinical management." (PMID 32870234, 2020). "Thus, we also investigated the relationship of MGMT promoter methylation and IDH1/2 mutation status with multifocal tumor growth and tumor contact to the SVZ." (PMID 34966832, 2020). "HPLC analysis was performed using frozen tumor samples from 21 patients, and MGMT methylation status could be determined for all patients." (PMID 33203454, 2020).
tumor (continued). "Measurement of MGMT expression might help assess the tumor sensitivity to TMZ but this needs further systematic investigation." (PMID 32132978, 2020). "We hypothesized that the quantitative 23Na signal correlates with tissue-specific tumor compartments and serves as a non-invasive predictor of tumor grade, IDH mutation and MGMT status." (PMID 33002860, 2020). "Additionally, controversial genes such as THBS1 and MGMT can be added to this system to help clinicians judge the situation of each tumor." (PMID 33014773, 2020). "TERT promoter mutation C250T and MGMT promoter methylation were significantly associated with tumor growth in univariable analysis but not in multivariable analysis." (PMID 32388499, 2020). "However, a strong tendency was observed comparing miR-181d tumor expression between GBM patients with methylated MGMT promoter (p = 0.065)." (PMID 33050332, 2020). "However, only anti‐MGMT‐02 peptide autoantibodies had a higher coverage of peptide than the preoperative when tumor recurrence developed." (PMID 31210005, 2019). "Our results show that a subset of GISTs WT for KIT and PDGFRA, including their largest pathogenetically characterized subpopulation, i.e., the SDH-deficient ones, is significantly enriched in MGMT-methylated cases, with SDH-deficient GISTs featuring the highest prevalence of this tumor variant." (PMID 30616628, 2019). "Contamination of the tumor tissue with normal and/or inflammatory cells also might lead to an incorrect estimation of the grade of MGMT promoter methylation." (PMID 31766430, 2019). "It means that not all cells harbour a deletion of one MGMT allele and that the heterogeneity is more evident in tumour bulk." (PMID 30984267, 2019). "Limitations of existing assays have usually resulted in binary classification of tumor MGMT status, making it difficult to assess whether the distinction between tumors with low MGMT and those that are completely lacking MGMT is clinically important." (PMID 30811507, 2019). "However, in terms of OS, patients characterized by an MGMT methylated GBM have an advantage of 12 months with respect to patients with an MGMT unmethylated tumor." (PMID 32039032, 2019). "Therefore, the presence of MGMT is considered to be the main reason for the resistance of tumor cells to alkylating agents." (PMID 31814867, 2019). "Moreover, the only patient with anaplastic transformation, dying from his tumor after two recurrences, was MGMT promoter methylated." (PMID 31362435, 2019). "In our study, we evaluated whether the combination of the molecular biomarker MGMT and image-based tumor heterogeneity computed using radiomics analysis would produce more accurate overall survival (OS) classification than MGMT alone." (PMID 30774763, 2019). "A high MGMT expression level is mechanistically linked to TMZ resistance in GBM, and elevated MGMT expression and/or the lack of MGMT promoter hypermethylation in patient tumor specimens is associated with worse outcomes in GBM patients treated with TMZ." (PMID 31053733, 2019). "Tumor site, both pre-operative and post-operative tumor volumes, ΔVT2T1, EOR, Ki67 expression, IDH1/2 gene mutation, 1p/19q co-deletion, molecular class, and methylation status of the MGMT promoter were associated with PFS at Cox univariate analysis." (PMID 31877896, 2019). "Testing MGMT promoter methylation not only in the primary tumor, but also in relapse might be useful." (PMID 31766430, 2019). "We validated its value in patients at different time points learning that the coverage ratio of all five autoantibody peptides had decreased 30 days after operation compared to levels before surgery; however, only MGMT‐02 peptide reached preoperative levels when tumor recurrence developed." (PMID 31210005, 2019). "In 80% of all cases the MGMT methylation was homogenous throughout the tumor." (PMID 31766430, 2019). "Tumor cells were positive for IDH1 mutation and positive for MGMT methylation status." (PMID 31929892, 2019).